SNRPC (small nuclear ribonucleoprotein polypeptide C)
Description:
Component of the spliceosomal U1 snRNP, which is essential for recognition of the pre-mRNA 5' splice-site and the subsequent assembly of the spliceosome. SNRPC/U1-C is directly involved in initial 5' splice-site recognition for both constitutive and regulated alternative splicing. The interaction with the 5' splice-site seems to precede base-pairing between the pre-mRNA and the U1 snRNA. Stimulates commitment or early (E) complex formation by stabilizing the base pairing of the 5' end of the U1 snRNA and the 5' splice-site region.
Synonyms: U1-C; U1C; Yhc1
Tractability: Small molecule: a structure with a bound ligand is known; it has a binding pocket of medium quality. PROTAC: ubiquitination databases record sites on it; its protein half-life has been measured.
Gene: Protein-coding gene on chromosome 6 (34,757,454 to 34,773,857, forward strand). Ensembl gene ENSG00000124562.
Subcellular location: Nucleus
Subcellular location (Human Protein Atlas): Nucleoplasm
Pathways (Reactome):
Metabolism of RNA: mRNA Polyadenylation; mRNA Splicing - Major Pathway
Gene Ontology:
Molecular function: protein binding; protein homodimerization activity; RNA binding; single-stranded RNA binding; U1 snRNA binding; zinc ion binding; pre-mRNA 5'-splice site binding; mRNA binding; nucleic acid binding
Biological process: mRNA splicing, via spliceosome; spliceosomal snRNP assembly; mRNA 5'-splice site recognition
Cellular component: Cajal body; nucleoplasm; nucleus; precatalytic spliceosome; spliceosomal complex; U1 snRNP; commitment complex; U2-type prespliceosome
Genetic constraint (gnomAD): Loss-of-function variants: 4 observed, 10.12 expected, observed/expected ratio (o/e) 0.4, 90% interval 0.19 to 0.9. The upper end of that interval is the gene's LOEUF score, 0.9, which puts it in group 3 of 6, group 1 being the genes least tolerant of losing a copy. Missense variants: 93 observed, 157.99 expected, observed/expected ratio (o/e) 0.59, 90% interval 0.5 to 0.7. Synonymous variants: 41 observed, 41.71 expected, observed/expected ratio (o/e) 0.98, 90% interval 0.76 to 1.28.
Homologues: Orthologues: chimpanzee SNRPC (100% identical), macaque SNRPC (100% identical), mouse Snrpc (99% identical), pig SNRPC (98% identical), rabbit SNRPC (95% identical), tropical clawed frog snrpc (90% identical), dog SNRPC (87% identical), zebrafish snrpc (86% identical), Caenorhabditis elegans snrp-3 (53% identical).
Diseases named in the same sentence as SNRPC in open-access papers:
SNRPC is named in the same sentence as 30 diseases in open-access papers, as found by Europe PMC text mining. Sharing a sentence is not in itself a finding about the gene and the disease. The quoted sentences say what the papers report.
hepatocellular carcinoma (4 papers, 2021 to 2024). A malignant tumor that arises from hepatocytes. "Small nuclear ribonucleoprotein polypeptide C (SNRPC) was highly up‐regulated in hepatocellular carcinoma (HCC) tissues and correlated with poor outcome in patients with HCC." (PMID 33934562, 2021). "SNRPC, PKB, and DCK have been discovered to significantly correlate with patient outcomes and immune cell infiltration in hepatocellular carcinoma." (PMID 35659304, 2022).
ovarian carcinoma (2 papers, 2023 to 2024). A malignant neoplasm originating from the surface ovarian epithelium. "The same trend of changes in the POM121, EDC4, and SNRPC genes was also found in ovarian cancer." (PMID 37409345, 2023).
endometrial cancer (1 paper, 2022). Primary or metastatic malignant neoplasm involving the endometrium (mucous membrane that lines the endometrial cavity). "SNRPC, PRELID1, EIF2S2, and NDUFB9, four of the model’s genes, were discovered to have higher levels of expression in endometrial cancer than in nearby tissues (*P<0.05, **P<0.01, ***P<0.001)." (PMID 36185238, 2022). "EIF2S2, SNRPC, PRELID1, and NDUFB9 were all up-regulated in endometrial cancer tissues, according to PCR results." (PMID 36185238, 2022). "We created an LLPS-related predictive model for endometrial cancer by extensive study, and it consists of four genes: EIF2S2, SNRPC, PRELID1, and NDUFB9." (PMID 36185238, 2022).
liver cancer (1 paper, 2023). An epithelial or non-epithelial malignant neoplasm that arises from the liver. "SNRPC is one of the specific protein components encoding U1 small ribonucleoprotein (snRNP) granules and is upregulated and prognostically related in liver cancer patients." (PMID 37409345, 2023).
Obesity (1 paper, 2024). Accumulation of substantial excess body fat. "The second region contains multiple genes around SNRPC, a gene locus with several well-studied variants associated with BMI and obesity." (PMID 38271473, 2024).
Vertigo (1 paper, 2022). An abnormal sensation of spinning while the body is actually stationary. "The sQTL-based TWAS identified 148 genes associated with vertigo, such as MTERFD2 (PTWAS = 0.003), C12orf73 (PTWAS = 0.027), and SNRPC (PTWAS = 0.003)." (PMID 36519156, 2022).
cancer (3 papers, 2021 to 2024). A tumor composed of atypical neoplastic, often pleomorphic cells that invade other tissues. "Small nuclear ribonucleoprotein polypeptide C (SNRPC), a subunit of U1 snRNP, has been connected to the acquisition of oncogenic character in TNBC cancer cells." (PMID 39795985, 2024). "According to certain studies, the four model genes EIF2S2, SNRPC, PRELID1, and NDUFB9 have significant roles in the development of cancer." (PMID 36185238, 2022).
tumor (3 papers, 2017 to 2024). "SNRPC expression was up‐regulated in HCC versus healthy control subjects and was positively correlated with advanced tumor grade and tumor stage, which were obtained from The Cancer Genome Atlas (TCGA) datasets." (PMID 33934562, 2021). "The oncogene JAK1 contained a high impact mutation within aggressive PET-10 tumor, while high impact mutations were identified in CARD11, NF2 and ORC1 within aggressive PET-20, and in DPY19L2 and SNRPC within non-aggressive PET-24." (PMID 29100308, 2017).
SNRPC also shares sentences with these, for which no sentence is quoted: breast carcinoma (2 papers); autoimmune disease (1); B-cell non-Hodgkin lymphoma (1); breast adenocarcinoma (1); cervical adenocarcinoma (1); cervical squamous cell carcinoma (1); colorectal cancer (1); connective tissue diseases (1); endometrial adenocarcinoma (1); esophageal adenocarcinoma (1); glioblastoma multiforme (1); lymphoma (1); melanoma (1); mixed connective tissue disease (1); ovarian adenocarcinoma (1); primary biliary cirrhosis (1); prostate carcinoma (1); rectal cancer (1); rheumatic diseases (1); rheumatoid arthritis (1); squamous cell lung carcinoma (1); virus infection (1).